CBS (cystathionine beta-synthase)
Diseases named in the same sentence as CBS in open-access papers (continued):
Sharing a sentence is not in itself a finding about the gene and the disease.
hyperhomocysteinemia (continued). "The association of hyperhomocysteinemia with NTD risk implicates enzymes such as MTR, BHMT, and CBS that degrade homocysteine." (PMID 17035141, 2006). "As one possibility, hepatic protein levels of BHMT and CBS may be saturated both in congenic and ExHC rats since both strains also develop homocysteinemia." (PMID 36810603, 2023). "Moreover, hyperhomocysteinemia, an established stroke risk factor, is found to impair ICH-enhanced CBS expression and delay spontaneous hematoma clearance, while administration of an H2S donor facilitated hematoma resolution in mice with hyperhomocysteinemia." (PMID 37601043, 2023). "In addition, hyperhomocysteinemia is also a hereditary disorder that results from genetic defects of the genes for CBS or methylenetetrahydrofolate reductase (MTHFR), genes that metabolize homocysteine by transulfuration or remethylation, respectively." (PMID 35204708, 2022). "In addition, low levels of (mRNA) Nrf1 have been observed in Cystathionine β synthase (CBS) heterozygous-null mice modeling hyperhomocysteinemia, a syndrome characterized by skeletal muscle weakness and fatigability." (PMID 34359231, 2021). "A main finding of our study is that H2S exerts a protective action against behavioral abnormalities of rats with maternal hyperhomocysteinemia (hHcy) in late postnatal life because of mitigating oxidative stress and restoration of CBS activity/expression and H2S brain level." (PMID 32630731, 2020). "In mice model of homocysteinemia, completely lacking of cystathionine β-synthase as a result of homozygous mutation in the CBS, severe growth retardation and significantly reduced lifespan (about 5 weeks) were observed." (PMID 30243020, 2018). "An unsolved issue is represented by question of whether the low H2S plasma levels observed in CKD/ESRD patients result from downregulation of CBS and CSE mediated by hyperhomocysteinemia or if this decrease should be attributed to other causes." (PMID 28753969, 2017). "We assessed the risk of hyperhomocysteinemia with MTHFR, MS and CBS genotypes." (PMID 22470444, 2012). "Additionally, recent studies have observed that hyperhomocysteinemia was related to a reduction in Nrf-2/HO-1 expression, a finding in accordance with the lower levels of CBS and Nrf-2 detected in OA-DB patients and db/db mice in our current and previous studies." (PMID 35453313, 2022). "Apart from the well-known risk factors triggered by IR, hyperhomocysteinemia is also present in PCOS due to the dysregulation of enzymes participating in homocysteine metabolism [i.e., Methyltetrahydrofolate Reductase (MTHFR) and hepatic Cystathione β-Synthase (CBS)]." (PMID 35877459, 2022). "Betaine has been used for more than 30 years in pyridoxine non-responsive cystathionine beta-synthase (pnrCBS) and cobalamin C (cblC) deficiencies to lower the hyperhomocysteinemia, although little is known about the optimal therapeutic dosage and its pharmacokinetic in these patients." (PMID 36376887, 2022). "Indeed, hyperhomocysteinemia due to a lack of CBS has been associated with several human visual disorders, such as DR and AMD." (PMID 32344885, 2020). "Nutritional deficiency of folic acid and vitamin B6 and/or B12 and renal insufficiency often cause relatively mild hyperhomocysteinemia, while genetic disorders such as mutations in N-5,10-methylenetetrahydrofolate reductase (MTHFR) and CBS may result in moderate and severe hyperhomocysteinemia." (PMID 31885816, 2019). "Deficiency of the metabolic enzymes [e.g., betaine homocysteine methyltransferase (BHMT), cystathionine β-synthase (CBS), and cystathionine γ-lyase (CTH)] involved in these two pathways can lead to hyperhomocysteinemia." (PMID 34393786, 2021). "Patients with CKD and ESRD show lower H2S plasma levels, which can result from downregulation of CBS and CSE, mediated by hyperhomocysteinemia." (PMID 30781775, 2019).
hyperhomocysteinemia (continued). "Also, a hyperhomocysteinemia model—CSE and CBS deletion—abrogated fasting-induced protection from myocardial ischemic injury." (PMID 33806545, 2021). "Severe homocysteinemias (between 100 and 500 μmol/l) are usually not seen in adults but only observed in newborns with inborn cystathionine-ß-synthase (CBS) defects." (PMID 34050373, 2021). "CBS is of great importance to regulate homocysteine levels in vivo because mice lacking CBS behave hyperhomocysteinemia and hypermethioninemia." (PMID 32477150, 2020). "However, in contrast to patients with classical homocysteinemia, plasma CBS activity never reached undetectable levels following givosiran treatment." (PMID 38974609, 2024). "Hyperhomocysteinemia may arise due to several reasons, including decreased expression or activity of the enzymes methylenetetrahydrofolate reductase (MTHFR), methionine synthase (MS), CBS, or CSE." (PMID 37237961, 2023). "Therefore, the lack of CBS will lead to the abnormal accumulation of Hcy and the occurrence of related diseases such as homocystinuria, homocysteinemia, and hypermethioninemia." (PMID 36727029, 2022). "This fact, along with the synergistic relationship between hyperglycaemia and hyperhomocysteinemia, could explain the negative CBS/hyperglycaemia correlation detected in our study." (PMID 35453313, 2022).
colon cancer (52 papers, 2012 to 2025). "CBS fosters the development and aggressiveness of colon cancer, whereas lower CBS levels are linked to glioma progression, indicating its oncogenic or tumor-suppressive functions depending on the context." (PMID 40416363, 2025). "Cancers of the colon, ovaries, prostate, and breast belong to the group of human diseases associated with a pathological upregulation of CBS and CBS-dependent H2S production." (PMID 34439739, 2021). "ShRNA-mediated silencing, as well as pharmacological inhibition of CBS caused a significant inhibition of the proliferation of colon cancer cells in vitro and in vivo (in tumor-bearing nude mice)." (PMID 27808278, 2016). "For instance, human mucosa tissue displays relatively higher CBS expression level compared to other tissues, and CBS knockdown results in decreased growth of colon tumor xenograft and reduced neovessel density." (PMID 40305883, 2025). "It is worth noting that overexpression of CBS and supplementation of exogenous H2S can inhibit the proliferation, colony formation, migration, and hepatic metastasis of colon cancer cells." (PMID 40442106, 2025). "The CBS protein levels in human colon cancer specimens closely correlated to the disease severity and tumor stage, and more advanced tumors expressed higher levels of CBS with higher expression of vascular endothelial growth factor (VEGF)." (PMID 37111185, 2023). "Inhibition of CBS has shown anti-tumor activity, particularly in colon cancer, ovarian cancer, and breast cancer, whereas the consequence of CSE or 3MST inhibition remains largely unexplored in cancer cells." (PMID 37483514, 2023). "Based on prior in vivo studies using other forms of cancer (e.g., colon cancer, ovarian cancer, or other forms of breast cancer) we anticipate that inhibition of CBS or 3-MST will suppress cancer cell proliferation." (PMID 36978895, 2023). "In 2013, it was demonstrated that colon cancer cells show increased expression of CBS, and use its product, H2S, to support their cellular bioenergetics, proliferation, growth, and angiogenesis." (PMID 36978895, 2023). "Studies reported that CBS is highly expressed in colon cancer, ovarian cancer, prostate cancer, and breast cancer." (PMID 36733341, 2023). "The CBS gene is often found to be upregulated in colon cancer, ovarian cancer, breast cancer, thyroid cancer, and gallbladder adenocarcinoma tissues." (PMID 37627515, 2023). "The liver (HepG2 and Hepa 1-6) and colon cancer (CT-26) cell lines were chosen for H2S-level investigation, due to their overexpression of CBS and CSE for the biosynthesis of endogenous H2S." (PMID 38162986, 2023). "In colon cancer cells, tumor-derived H2S, produced mainly by CBS, inhibits ferroptosis by stabilizing SLC7A11 via sulfhydration at cysteine 9133." (PMID 37381723, 2023). "The current studies were set up to investigate if CBS or 3-MST regulates CyR61 in colon cancer cells in the context of the regulation of proliferation, migration, and survival." (PMID 36113340, 2022). "We have used HCT116 cells, a human colon cancer cell line in vitro, where the importance of both CyR61 and the H2S producing enzymes CBS and 3-MST have previously been demonstrated." (PMID 36113340, 2022). "In rat models of colon cancer and ovarian cancer, CBS silencing inhibited tumor growth and neovessel density." (PMID 35684331, 2022). "An increasing body of evidence points to the key roles of CBS in tumor progressions, such as ovarian cancer and colon cancer." (PMID 35422048, 2022). "CBS was overexpressed in primary epithelial tissues, ovarian cancer, and multiple ovarian cancer cell line specimens similar to colon cancer cells." (PMID 35684331, 2022).
colon cancer (continued). "IHC and western blotting analysis using human colon cancer specimens revealed a distinct increased expression of CBS in tumor tissues compared with adjacent normal mucosa slices." (PMID 35172821, 2022). "In conclusion, H2S produced from CBS serves to (i) maintain colon cancer cellular bioenergetics, thereby supporting tumor growth and proliferation, and (ii) promote angiogenesis and vasorelaxation, consequently providing the tumor with blood and nutrients." (PMID 35684331, 2022). "Like non-malignant colon mucosa cells, epithelial cell lines from colon cancer exhibit selective CBS upregulation and increased H2S development." (PMID 35684331, 2022). "Many studies have shown that CBS is involved in the growth of several types of cancer, such as colon cancer and liver cancer." (PMID 35795862, 2022). "Cell fractionation studies were also conducted to investigate CBS location in colon cancer cells, with the results showing that CBS is habitually localized to the cytosol, but mitochondrial translocation is also possible." (PMID 35684331, 2022). "By altering the expression or activity of CBS, CBS has been shown to promote proliferation of colon cancer cells." (PMID 36088423, 2022). "Overexpression of CBS and exogenous provision of H2S inhibited colon cancer cell proliferation and migration both in vivo and in vitro." (PMID 35172821, 2022). "Overexpression of CBS and exogenous H2S inhibited colon cancer cell proliferation and migration in vitro." (PMID 35172821, 2022). "Our results show that overexpression of CBS/H2S indeed exerts an inhibitory effect on the proliferation and migration of colon cancer cells both in vitro and in vivo." (PMID 35172821, 2022). "The pharmacological properties of these compounds were evaluated in cell-free assays with recombinant human CBS protein, the human colon cancer cell line HCT116, and in vivo using various tumor-bearing mice models." (PMID 34439739, 2021). "Further analysis revealed that CBS-synthesized H2S suppressed the colon cancer tumor suppressor miR-215-5p, increasing both thymidylate synthase and epiregulin (an EGFR signaling activator)." (PMID 35366284, 2021). "Elevated H2S-producing enzymes have been observed in multiple cancer types, and depletion of CBS or CTH activities results in the suppression of tumor growth in colon cancer, lung cancer, prostate cancer, and breast cancer." (PMID 34207284, 2021). "The functional role of CBS- or 3-MST-derived H2S in colon cancer cells has been studied extensively." (PMID 33499368, 2021). "Silencing H2S producing enzyme, CBS, reduces the formation of tumor blood vessels in colon cancer and ovarian cancer." (PMID 34207284, 2021). "In 2013, we first reported the aberrant upregulation of CBS in human colon tumor tissue and colon cancer-derived cell lines and demonstrated that inhibition of CBS expression and/or activity had antitumor effects." (PMID 34439739, 2021). "CBS, which catalyzes H2S by driving beta-replacement, has been observed to be selectively upregulated in colon cancer, ovarian cancer, breast cancer, thyroid cancer, and gallbladder adenocarcinoma tissues." (PMID 34207284, 2021). "In 2013, we have discovered that CBS is upregulated and H2S generation is increased in primary human colon cancer tissues compared to the surrounding (nominally healthy) tissues." (PMID 33499368, 2021). "Further studies revealed that premalignant colonic tubular adenomas (low-grade epithelial dysplasia) exhibited increased CBS expression, indicating that increased CBS expression is an early event in colon cancer." (PMID 35366284, 2021). "For instance, in colon cancer cells CBS silencing suppresses basal mitochondrial function (oxygen consumption, ATP generation) and similar effects are seen with CBS silencing in ovarian cancer cells and with 3-MST silencing in hepatoma cells." (PMID 33499368, 2021).
colon cancer (continued). "A role for GAPDH in cancer comes from the observation that CBS knockdown in colon cancer cell lines lowers GAPDH enzymatic activity." (PMID 35366284, 2021). "In particular in human colon cancer, the most significant upregulation in tumor tissue (compared to surrounding tissue) was noted in CBS, with a trend for increase for 3-MST." (PMID 32183148, 2020). "In colon cancer cells, CBS silencing resulted in a reduction of basal cellular respiration, ATP synthesis, maximal respiration and spare respiratory capacity in vitro, and the reduction of tumor growth and angiogenesis in vivo." (PMID 32365821, 2020). "Pharmacological inhibition of CBS in these colon cancer cell lines reduced cell proliferation, invasion, and migration along with suppressed glycolysis and mitochondrial function, suggesting that H2S can facilitate tumor growth." (PMID 33330130, 2020). "In colon cancer-derived epithelial cell lines, CBS levels are upregulated with concomitantly increased H2S production." (PMID 33330130, 2020). "Increased expression of CBS and H2S has been validated in colon cancer tissue samples and cell lines." (PMID 32194794, 2020). "Follow-up studies evaluated the inhibitory effect of sikokianin C on the proliferation of HT29 cells (a human colon cancer cell line expressing high levels of CBS)." (PMID 32365821, 2020). "The current study indicated that inhibition of H2S synthesis utilizing AOAA, a classic inhibitor of CBS, significantly sensitized colon cancer cells to OXA both in vitro and in vivo." (PMID 32194794, 2020). "In contrast, in the current, murine colon cancer cell line, CBS (mRNA or protein) was undetectable (and, accordingly, the CBS inhibitor AOAA was without significant biological effects), while 3-MST was highly expressed." (PMID 32183148, 2020). "A series of studies from the Hellmich group characterized the oncogenic role of CBS in colon cancer." (PMID 30050925, 2018). "Through modification of CBS expression (overexpression or RNAi knockdown) or CBS activity (allosteric activator SAM or the inhibitor aminooxyacetate) in the HCT116 colon cancer cell line, they demonstrated that CBS promoted cancer cell proliferation." (PMID 30050925, 2018). "Aminooxyacetic acid (AOAA) is a cystathionine-β-synthase (CBS) inhibitor, studies showed it suppresses the proliferation of colon cancer cells in vitro and reduces tumor growth in vivo." (PMID 30463528, 2018). "Abnormal de-regulation of CBS in Down syndrome, colon cancer, ovarian cancer or glioma as well as breast and lung cancer has been reported." (PMID 30258181, 2018). "Recent data support the concept of using SAM as a chemopreventive agent in HCC and colon cancer, consistent with the proposed tumor-suppressive role of CBS in HCC." (PMID 30050925, 2018). "Downregulation of CBS through promoter methylation has been observed in multiple gastric cancer cell lines and four colon cancer cell lines (including HCT116)." (PMID 30050925, 2018). "H2S was identified to be responsible for such metabolic and bioenergetic rewiring in colon cancer cells, as CBS expression and activity correlated with H2S production and exogenous H2S stimulated cell proliferation and bioenergetics." (PMID 30050925, 2018). "Tumor-derived hydrogen sulfide, produced by cystathionine-beta-synthase, stimulates bioenergetics, cell proliferation, and angiogenesis in colon cancer." (PMID 27461275, 2016).